CLU (clusterin)
Diseases named in the same sentence as CLU in open-access papers (continued):
Sharing a sentence is not in itself a finding about the gene and the disease.
eating disorder (2 papers, 2020 to 2021). A broad group of psychological disorders with abnormal eating behaviors leading to physiological effects from overeating or insufficient food intake. "Moreover, an increase of this protein was observed in the plasma of obese patients with food addiction, suggesting the implication of CLU in this eating disorder." (PMID 33994910, 2021).
endothelial dysfunction (2 papers, 2019). In vascular diseases, endothelial dysfunction is a systemic pathological state of the endothelium (the inner lining of blood vessels) and can be broadly defined as an imbalance between vasodilating and vasoconstricting substances produced by (or acting on) the endothelium. "Clusterin has vital tasks such as, endothelial cell death triggered by light chain preventing the artery endothelial dysfunction, ensuring stabilization of the protein, and removal of the dissolved and damaged proteins." (PMID 32257894, 2019).
epidermoid carcinoma (2 papers, 2008 to 2020). "Clusterin, a secreted mammalian chaperone associated with stress-associated cell survival (anti-apoptotic gene) is also downregulated in DC, contrasting with its overexpression in several human cancers such as prostate, breast, and squamous cell carcinoma." (PMID 18433489, 2008).
follicular dendritic cell sarcoma (2 papers, 2015 to 2025). A neoplasm composed of spindle to ovoid cells which have morphologic and immunophenotypic characteristics of follicular dendritic cells. "Follicular dendritic cell sarcoma (FDCS) is specifically immunopositive to CD21, CD35, and/or CD23, vimentin, fascin, HLA-DR, EMA, D2-40, clusterin, and CXCL13." (PMID 25889780, 2015).
Fuch’s corneal dystrophy (2 papers, 2009 to 2023). "Clusterin has been described as being overexpressed in corneal diseases, including severe ocular surface diseases and Fuchs’ endothelial dystrophy." (PMID 20019877, 2009). "Clusterin has been reported to express in normal corneal endothelilum, to increase in corneal endothelium with Fuchs’ endothelial dystrophy, and to decrease in corneas with bullous keratopthay." (PMID 20019877, 2009). "Exogenous clusterin may be useful as a protective agent during intraocular surgery in old patients and patients with Fuchs endothelial dystrophy or bullous keratpathy." (PMID 20019877, 2009).
hand osteoarthritis (2 papers, 2018). "Lower levels of serum clusterin has been found associated with pain in patients with hand osteoarthritis compared to healthy controls." (PMID 30555396, 2018).
influenza (2 papers, 2013 to 2024). An acute viral infection of the respiratory tract, occurring in isolated cases, in epidemics, or in pandemics; it is caused by serologically different strains of viruses (influenzaviruses) designated A, B, and C, has a 3-day incubation period, and usually lasts for 3 to 10 days. "As in the embryonic lung, clusterin is re-expressed in the lung tissue including in SBECs following influenza infection." (PMID 23940685, 2013). "However, following influenza infection, clusterin expression was induced in the lung." (PMID 23940685, 2013).
intestinal cancer (2 papers, 2015 to 2020). "In the Min mouse model for WNT signaling-driven intestinal cancer, CLU is induced at early stages of tumor development." (PMID 26399194, 2015). "It remains to be elucidated whether a comparable hierarchical relationship between LGR5+ cells and CLU+ cells is conserved in human intestinal cancer tissues." (PMID 31906589, 2020).
intestinal tumor (2 papers, 2022 to 2025). "Our analysis results show that S100A6 and CLU exhibit high expression in intestinal tumor tissue." (PMID 41009818, 2025).
ischemic stroke (2 papers, 2018 to 2019). A stroke disorder caused by obstruction of blood flow to the brain, due to thrombotic (local blood clot formation) or embolic (due to a blood clot or other material traveling from another site) event. "The same study analysed serum clusterin levels in human ischemic stroke patients and observed a 1.16-fold elevation." (PMID 31882899, 2019). "Moreover, significant changes in clusterin have been detected in patients with AMI and increased levels of selectin L (SELL) are associated with ischemic stroke." (PMID 29530068, 2018).
late-onset Alzheimers disease (2 papers, 2011 to 2025). This is the most common form of the disease, which happens to people age 65 and older. "Recent GWAS and subsequent confirmation studies reported several single-nucleotide polymorphisms (SNPs) at the CLU, CR1 and PICALM loci in association with late-onset Alzheimer's disease (AD)." (PMID 21912625, 2011).
leukoencephalopathies (2 papers, 2016 to 2019). "They nevertheless observed a correlation between clusterin levels and white matter pathology scores, not only in CADASIL, but also in other leukoencephalopathies, suggesting a more general role of clusterin in ischemic SVD." (PMID 31798396, 2019). "We found that clusterin immunostaining was significantly increased in the frontal white matter of CADASIL and pontine autosomal dominant microangiopathy and leukoencephalopathy subjects." (PMID 25940137, 2016).
neuroendocrine tumor (2 papers, 2024 to 2025). "Additionally, clusterin (CLU), a ubiquitous multifunctional secretory sulfated glycoprotein, plays roles in apoptosis and cell differentiation and is overexpressed in various tumors, including neuroendocrine tumors." (PMID 39937015, 2025).
neuropathies (2 papers, 2016 to 2022). "Our result that serpinA3N treatment reduced nNOS and p‐p3862, 63 might be suggestive of an inhibitory role for clusterin in NMDAR‐related neuropathies." (PMID 34897996, 2022).
non-alcoholic steatohepatitis (2 papers, 2019 to 2020). "Our previous studies indicated that hepatocyte-specific overexpression of clusterin alleviates methionine choline-deficient (MCD) diet-induced non-alcoholic steatohepatitis (NASH) by activating nuclear factor erythroid 2-related factor 2 (Nrf2)." (PMID 33060605, 2020).
Oral Squamous Cell Carcinoma (2 papers, 2019 to 2023). "In conclusion, this review highlights the crucial role of Clusterin in Oral Squamous Cell Carcinoma, specifically its isoforms, in the development and progression of OSCC." (PMID 37239129, 2023). "On the contrary, RBP4 was recently reported as a potential biomarker of oral squamous cell carcinoma, in combination with clusterin, haptoglobin, complement C3c, and proapolipoprotein A1." (PMID 30813269, 2019).
osteoporosis (2 papers, 2022 to 2023). A condition of reduced bone mass, with decreased cortical thickness and a decrease in the number and size of the trabeculae of cancellous bone (but normal chemical composition), resulting in increased fracture incidence. "Ex vivo knock-down of clusterin restored proliferative capability and improved markers of tissue damage repair in human myoblasts from elderly patients with osteoporosis." (PMID 36678864, 2023). "CLU appears also to be involved in the modulation of bone metabolism in specific aging-related diseases, including osteoarthritis (OA) and osteoporosis (OP)." (PMID 35456459, 2022).
parasite infection (2 papers, 2017 to 2022). "Genes encoding CLU, SPARC and PLAU, were also higher more than 1fold, log2 in Holstein cells and modulated by parasite infection." (PMID 35061738, 2022).
pituitary adenomas (2 papers, 2011 to 2022). "Studies reported alterations in the expression of Clusterin at transcription and translational levels in pituitary adenomas with the help of microarray and LC-MS-MS." (PMID 36176404, 2022). "As distribution of FOXL2 appeared to mirror clusterin expression in pituitary adenomas, we tested whether FOXL2 stimulates clusterin in gonadotroph cells." (PMID 21464964, 2011).
polycystic ovary syndrome (2 papers, 2020 to 2026). A disorder that manifests as multiple cysts on the ovaries. "Therefore, the present study aimed to evaluate serum clusterin levels in women with polycystic ovary syndrome and to investigate its associations with metabolic and hormonal parameters, as well as its diagnostic value and metabolic relevance within the PCOS population." (PMID 41515662, 2026).
prostate hyperplasia (2 papers, 2011 to 2022). "With increasing age, urinary levels of clusterin and corticosteroid-binding globulin increased and neprilysin levels decreased, all of which appear to play a role in prostate hyperplasia or carcinogenesis." (PMID 35886909, 2022). "Induction of prostatic hyperplasia in our model is accompanied with significant increase of the clusterin and IGF-1 expression in ventral lobe of rat prostate, while the TGF-β1 expression was significantly decreased." (PMID 22195697, 2011).
psychological distress (2 papers, 2018 to 2020). "There, we found hemopexin, complement factor B, and clusterin, among others, to be positively associated with increased psychological distress in CWP." (PMID 32719459, 2020). "Several proteoforms of clusterin were significantly altered and associated with higher psychological distress." (PMID 30555396, 2018).
Rett syndrome (2 papers, 2019 to 2023). A severe neurodevelopmental disorder affecting the central nervous system.
sarcopenia (2 papers, 2019 to 2025). Progressive decline in muscle mass due to aging which results in decreased functional capacity of muscles. "These processes eventually lead to a premature degenerative process and aging, pointing out a potential role of CLU as a new OP diagnostic marker for muscular degeneration and a potential target for specific therapeutic intervention in OP related sarcopenia." (PMID 30967152, 2019). "Moreover, CLU silencing points out its role in the modulation of tissue damage repair and inflammation, proposing it as a new diagnostic marker for muscle degeneration and a potential target for specific therapeutic intervention in OP related sarcopenia." (PMID 30967152, 2019). "We focused on the role of CLU, which is involved also in calcium metabolism, to clarify its function in these pathologies and its potential action in reduction of muscular mass leading to sarcopenia and its possible involvement in the inflammatory process that characterizes OP and OA condition." (PMID 30967152, 2019).
serous adenocarcinoma (2 papers, 2009). An adenocarcinoma that is characterized by the presence of papillary patterns and cellular budding. "We analysed the gene expression of CLU, ITGB3, CAPG, and PRAME in 30 advanced staged serous adenocarcinomas with quantitative real-time polymerase chain reaction (QPCR) and the protein levels were analysed in 98 serous adenocarcinomas with western blot for semiquantitative analysis." (PMID 19775429, 2009).
status epilepticus (2 papers, 2012 to 2024). Status epilepticus is defined as a continuous seizure lasting more than 30 min, or two or more seizures without full recovery of consciousness between any of them. "Induced status epilepticus leads to a sharp increase in clusterin mRNA in glial cells." (PMID 39063177, 2024). "Previous studies have implicated clusterin in the response to hypoxic/ischaemic injury in the brain, however it has also been described in dying neurons following status epilepticus raising the possibility that is a marker of nonspecific marker of neuronal damage." (PMID 22848862, 2012).
T-cell lymphoma (2 papers, 2006 to 2022). "When we compared three groups of B-cell lymphoma, T-cell lymphoma, and healthy dogs, the serum β2M (p=0.006), clusterin (p=0.01), immunoglobulin (Ig) heavy chain V region GOM (p=0.02), and plasminogen (p=0.02) were significantly higher in B-cell than T-cell lymphoma." (PMID 35765478, 2022). "In neoplastic B phenotypes, drastically differential increased protein levels were observed in Ig heavy chain V region GOM, clusterin, β2M, and plasminogen, while APOC1 was only notably elevated in T-cell lymphoma." (PMID 35765478, 2022). "When compared between B- and T-cell lymphomas, B-cell phenotypes had upregulated immunoglobulin (Ig) heavy chain V region GOM (p=0.02), clusterin (p=0.01), apolipoprotein C1 (APOC1, p=0.05), and plasminogen (p=0.02)." (PMID 35765478, 2022).
triple-negative breast carcinoma (2 papers, 2021 to 2025). An invasive breast carcinoma which is negative for expression of estrogen receptor (ER), progesterone receptor (PR), and human epidermal growth factor receptor 2 (HER2). "This study identifies the tumor-secreted chaperone clusterin (CLU) as a driver of white adipose tissue (WAT) depletion in triple-negative breast cancer (TNBC)." (PMID 41408487, 2025). "This study defines protein kinase D3 (PRKD3) to be the key regulator of clusterin (CLU) in promoting triple negative breast cancer (TNBC) tumor growth." (PMID 33643800, 2021).
acute pancreatitis (1 paper, 2020). An acute inflammatory process that leads to necrosis of the pancreatic parenchyma. "In a mouse model of acute pancreatitis, clusterin-deficient mice showed a more severe course of the disease." (PMID 32764517, 2020).
adrenocortical adenomas (1 paper, 2025). "Clusterin emerges as a potential biomarker for adrenocortical adenomas." (PMID 40190189, 2025).
ameloblastoma (1 paper, 2025). The most common odontogenic tumor, arising from the epithelial component of the embryonic tooth and usually affecting the molar-ramus region of the mandible or maxilla. "Considering the known functions of CLU, our results suggest that it is closely linked to the differentiation of a subset of ameloblastoma cells into neuroendocrine-like cells that express SYP and INSM1." (PMID 39937015, 2025). "We analyzed 36 ameloblastoma specimens for CD56, SYP, CgA, and clusterin (CLU) and examined limited samples for INSM1 expression by performing immunohistochemistry, transmission electron microscopy, and reverse transcriptase-polymerase chain reaction." (PMID 39937015, 2025).
astrocytoma (1 paper, 2025). "Here, we aimed to investigate the effects of CLU dysregulation on two human astrocytic cell lines: CCF-STTG1 astrocytoma cells and SV-40 immortalized normal human astrocytes." (PMID 39627493, 2025). "In the present study, we investigated the consequences of CLU downregulation in human astrocytes and described the molecular changes associated with siRNA silencing–mediated CLU dysregulation in CCF-STTG1 astrocytoma and SV-40 immortalized non-transformed human astrocyte cell lines." (PMID 39627493, 2025).
autosomal recessive polycystic kidney disease (1 paper, 2021). An inherited disorder characterized by the development of cysts affecting the collecting ducts. "Clusterin has also been identified as a component of renal cyst fluid in human autosomal recessive polycystic kidney disease (ARPKD) patients." (PMID 33798093, 2021).
Azoospermia (1 paper, 2024). Absence of any measurable level of sperm,whereby spermatozoa cannot be observed even after centrifugation of the semen pellet. "This preliminary investigation involved measuring and comparing the serum protein levels of PDIA1, PDIA3, MANF, GRP78, CLU, CRT, and CNX in patients diagnosed with idiopathic nonobstructive azoospermia and noninfertile male controls." (PMID 39237030, 2024).
B-Cell CLL (1 paper, 2017). "Intracellularly, CLU has been found to bind and inactivate apoptosis regulator BAX (BAX), thereby altering the ratio between pro-apoptotic BAX and anti-apoptotic B-Cell CLL/Lymphoma 2 proteins towards a pro-survival level." (PMID 28902909, 2017).
babesiosis (1 paper, 2014). Babesiosis refers to a condition caused by microscopic parasites that infect the red blood cells. "Complement activation in babesiosis was confirmed by clusterin and C3 increased expression." (PMID 24885808, 2014).
benign cystadenoma (1 paper, 2015). "A significant increasing cytoplasmic expression of clusterin was observed from the normal ovary, to benign cystadenoma, borderline tumor, and malignant epithelial carcinoma." (PMID 26293319, 2015).
bullous keratopathy (1 paper, 2021). "Multiple other studies have also reported changes in the expression of CLU in patients with corneal endothelial dystrophies, including FECD and bullous keratopathy." (PMID 33651877, 2021).
cataract (1 paper, 2023). Partial or complete opacity of the crystalline lens of one or both eyes that decreases visual acuity and eventually results in blindness. "Within the male cohort, three complement proteins (CLU, C6, and CFH) were downregulated in POAG patients compared to those with cataracts." (PMID 37763167, 2023).
Cerebral atrophy (1 paper, 2015). Atrophy (wasting, decrease in size of cells or tissue) affecting the cerebrum. "Expression of the top five differentially expressed genes found by GWAS - MS4A6A, CD2AP, INPP5D, MEF2C and CLU – all have good correlation with Braak stage and cerebral atrophy." (PMID 26202100, 2015).
cerebral palsy (1 paper, 2020). A group of disorders affecting the development of movement and posture, often accompanied by disturbances of sensation, perception, cognition, and behavior. "For example, the mouse model of cerebral palsy shows significantly higher levels of clusterin in the dying neurons, whereas heterozygous and homozygous clusterin knockout mice show significantly lower level of brain lesions in an allele-dose-dependent manner." (PMID 32084011, 2020).
cervical squamous cell carcinoma (1 paper, 2021). A squamous cell carcinoma arising from the cervical epithelium. "Additionally, studies have shown that concentrations of APOA1, APOE, and CLU were differentially expressed in cervical squamous cell carcinoma patients when compared to those with benign lesions and were associated with the histological classification or the processing of the cervical lesion." (PMID 33521130, 2021).
chlamydial infection (1 paper, 2024). "The consequences of CLU inactivation on a chlamydial infection could therefore be direct and/or indirect, which would make their assessment impossible." (PMID 39931630, 2024).
chronic heart failure (1 paper, 2020). "In contrast, that serum clusterin level decreased due to continuous consumption was associated with an unfavorable prognosis in patients with chronic heart failure." (PMID 33256720, 2020).
chronic liver failure (1 paper, 2020). Liver failure that develops slowly and gradually for some time, possibly for years, often as the result of cirrhosis, or malnutrition. "Based on the multiple biological functions of clusterin and the pathological features of ACLF, we hypothesize that serum clusterin may play an important role in the pathogenesis of ACLF and may serve as a novel biomarker for acute-on-chronic liver failure." (PMID 33381244, 2020). "Clusterin had better ability for predicting the prognosis of HBV-ACLF patients than did the model for end-stage liver disease (MELD) score and the chronic liver failure consortium (CLIF-C) ACLF score (MELD vs. clusterin: P = 0.012; CLIF-C ACLF vs. clusterin: P = 0.031)." (PMID 33381244, 2020).
chronic pancreatitis (1 paper, 2022). A chronic inflammatory process causing damage and fibrosis of the pancreatic parenchyma. "For example, clusterin (CLU) plays an essential role in pancreas regeneration and is expressed in chronic pancreatitis; α-amylase (AMY2B) is a characteristic gene for mature acinar cells, encoding a digestive enzyme." (PMID 35758781, 2022).
coagulation disorders (1 paper, 2025). "Twenty-four hours after exercise, during the recovery period, coagulation-related proteins and the complement factor CLU remained downregulated, which may lead to coagulation disorders and a reduced immune response speed in Mongolian horses that have undergone excessive exercise." (PMID 40646880, 2025).
colon adenocarcinoma (1 paper, 2020). "We further explored the prognostic relevance of CLU expression in CRC using the OncoLnc online system to analyse colon adenocarcinoma patient data from TCGA." (PMID 31906589, 2020).